INS (insulin)
Diseases named in the same sentence as INS in open-access papers (continued):
Sharing a sentence is not in itself a finding about the gene and the disease.
Hyperglycemia (continued). "Even though there is an increase in the number of beta cells and the level of insulin during pregnancy, a number of pregnant females are unable to increase insulin synthesis in response to insulin resistance, thereby developing hyperglycemia and subsequent gestational diabetes." (PMID 36475181, 2022). "The negative association between adult height and total insulin secretion was consistent with what we previously noted, i.e. that hyperglycemia can stimulate total insulin output (and insulin and C-peptide AUCs) to levels similar or even greater than in healthy subjects." (PMID 35358060, 2022). "Gut-derived glucagon-like peptide-1 (GLP-1) belongs to the family of incretin hormones, gastrointestinal hormones released after nutrient intake with the ability to increase insulin secretion in a glucose-dependent manner through pancreatic beta cells during periods of hyperglycaemia." (PMID 36077515, 2022). "In addition, HAEVa prevents the postprandial blood sugar level in insulin-resistant rats, which suggests a decrease in the occurrence of cancer related to permanent hyperglycemia." (PMID 36845227, 2022). "We hypothesize that, in a woman with HIP, once fetal beta cells start secreting insulin, fetal hyperinsulinemia persists with maternal hyperglycemia." (PMID 36540507, 2022). "A structured daily exercise training program may counteract hyperglycemia and reduce the need for insulin treatment." (PMID 35162066, 2022). "Therefore, disease progress is similar to treatment with insulin, thus, reducing hyperglycemia, hyperphagia and polydipsia." (PMID 35741335, 2022). "The preferential use of the liver to dispose a significant amount of the ingested glucose during first pass, along with a 60–70% hepatic clearance of insulin, protect the peripheral circulation from excessive hyperglycemia/hyperinsulinemia in the postprandial period." (PMID 35215472, 2022). "During insulin biosynthesis within β cells due to hyperglycemia, the formation of three disulfide bonds per one insulin molecule results in the release of millions of ROS molecules per minute; consequently, damage caused by ROS can contribute to β cell dysfunction." (PMID 35204118, 2022). "The results of this retrospective study indicate the InsulinAPP application using human insulin formulations was effective and safe for the management of hyperglycemia on a hospitalist-managed ward, with more than 70% BG measurements within the therapeutic range and a low rate of hypoglycemia." (PMID 35758838, 2022). "Hence, blocking Gcgr can restore hyperglycemia in rodent models with insufficient insulin secretion; however, this effect requires a certain number of β cells." (PMID 35784565, 2022). "Based on these findings, A. decursiva–derived 6-FU coumarin might be effective in controlling hyperglycemia by inhibiting α-glucosidase and attenuating the insulin signaling pathway via PTP1B inhibition." (PMID 36080485, 2022). "Moreover, GPX3 belongs to an adipokine cluster related to insulin sensitivity/hyperglycemia and lipid metabolism in humans." (PMID 35624726, 2022). "One of the largest cohort studies to date found that 76% of general medical inpatients received sliding-scale insulin, with these regimens not only failing to control hyperglycaemia but also resulting in more episodes of hypoglycaemia and longer hospital stays." (PMID 35329299, 2022). "In conclusion, the use of linagliptin in combination with insulin in hospitalized patients with SARS-CoV-2 and hyperglycemia reduces the risk of assisted mechanical ventilation by 74% and improves glucose control and pulmonary parameters related to clinical evolution and prognosis." (PMID 35017617, 2022). "The concept that subclinical insulin secretory defects may affect linear growth independently from hyperglycemia has been suggested by a small-sized study in CF, but further evidence arises from studies in type 1 diabetes and in healthy subjects." (PMID 35358060, 2022).
Hyperglycemia (continued). "SMBG aims to enhance patients’ ability to measure the fasting, pre-meal, and postprandial glycaemia, to adjust the insulin dose according to the measured values, to recognise and prevent hyperglycaemia, and to increase the frequency of glucose monitoring during physical activity or acute illness." (PMID 35052337, 2022). "Binding to adrenergic α2 and muscarinic M4 receptors contributes to salivation, while binding to muscarinic M3 may be related to insulin regulation and the development of hyperglycemia." (PMID 35890117, 2022). "Theoretically, lowering the insulin dose may consequently increase rates of hyperglycemia, however, studies have shown that decreasing the pre-Ramadan TDD of insulin does not subsequently increase the rate of hyperglycemia, DKA, or A1c." (PMID 35634376, 2022). "Possible reasons for this might be with advanced age there might be decreased in physical exercise, loss of muscle mass, and gain weight that in turn fatty cells had more resistant for insulin that increase hyperglycemia." (PMID 35114950, 2022). "In a meta-analysis including 35 trials of pharmacological interventions for GDM, metformin was reported as an effective alternative to insulin in the treatment of hyperglycaemia; however, supplemental insulin may be required in up to 50% of women." (PMID 35380983, 2022). "Notably, AD and PD show alterations in oxidative stress levels, hyperglycemia, mitochondrial dysfunction, glucose metabolism, insulin signaling, insulin resistance, and inflammatory processes." (PMID 35821802, 2022). "Increased fasting blood glucose (hyperglycemia) and insulin are also observed among PTSD patients." (PMID 36293361, 2022). "According to previous studies, approximately 10–20% of circulating immunoreactive insulin is proinsulin, which is cleared from the plasma slower than mature insulin —in the elderly, circulating proinsulin concentrations increase, as does hyperglycemia, which is related to the aging process." (PMID 35563231, 2022). "In vivo studies demonstrate that insulin improves mobilisation and stimulates the angiogenic function of EPCs, while in vitro studies demonstrate C-peptide reduces hyperglycaemia-induced dysfunction in mature vascular endothelial cells and stimulates ATP release from erythrocytes." (PMID 35222269, 2022). "However, prolonged hyperglycemia gives rise to glucose toxicity, which impairs insulin production and secretion, promoting a vicious cycle with ever-increasing glucose concentrations and ever-declining β-cell function, and eventually β-cell death." (PMID 35908073, 2022). "Hyperglycemia and abnormal insulin signaling may lead to cardiac defects by impairing the expression of key regulatory genes as well as posttranslational modification of transcription factors that may result in the modulation of crucial target genes." (PMID 36176990, 2022). "Using an insulin pump reduces fear of severe hyperglycemia and diabetic coma." (PMID 35915454, 2022). "Although insulin levels may be normal or even elevated in some diabetic patients, most tissues are unable to use glucose, resulting in hyperglycemia." (PMID 36305681, 2022). "Numerous regions were hypermethylated in foetal pancreas generated from hyperglycaemia oocytes, and differentially hypermethylated regions (hyper‐DMRs) in the promoters of several genes involved in insulin secretion, including a pancreas‐specific promoter that drives pancreatic transcription of Gck." (PMID 35802824, 2022). "In vivo, the CAER platform showed that the BGL responsively controlled INS release in order to control hyperglycemia and maintain the BGL in the normal range for up to 3 days; plus, there was good glycemic control without the added burden of hemodialysis in DN rabbits." (PMID 36296745, 2022).
Hyperglycemia (continued). "Finally, it is noteworthy that in addition to being greatly induced by hyperglycemia and inflammation that prevail in DM, AGEs by themselves can induce DM by diminishing peripheral insulin sensitivity and beta-cell insulin secretion." (PMID 35269546, 2022). "Collectively, the in vivo and in vitro data suggest that OCP exposure suppresses insulin secretion and promotes hyperglycemia, perhaps in part by altering β-cell function and promoting β-cell death, although the specific mechanism of action remains unclear." (PMID 35156417, 2022). "In hyperglycemia, it can be stimulated by AGEs, insulin and angiotensin II." (PMID 35052633, 2022). "This justifies applying the weight to the mealtime insulin bolus for the insulin delivery strategy to mitigate postprandial hyperglycaemia without significantly increasing hypoglycaemia risk." (PMID 35062427, 2022). "In addition, chronic fetal hyperglycemia has been shown to result in reduced insulin sensitivity, diminished protein synthesis, and fetal growth restriction." (PMID 35880402, 2022). "Therefore, currently available studies support that controlling hyperglycemia by pharmacological insulin administration or any other hypoglycemic agent and/or suppressing ROS are the best therapeutic strategies to prevent DC in diabetic individuals or animals." (PMID 35241966, 2022). "AIRg values trended higher in foals compared to horses but were not significantly different, further suggesting that foals may have a higher capacity to secrete insulin in response to hyperglycemia." (PMID 35030228, 2022). "If the foetus inherits the mutation, it will sense the maternal hyperglycaemia as normal (since the foetal pancreas will have the same glucose sensing defect) and there will be no increased foetal insulin secretion." (PMID 35445424, 2022). "Therefore, lifestyle interventions, such as those described in the present review, are important to improve tissue sensitivity to insulin and hence avoid marked hyperglycemia and hyperinsulinemia after meals." (PMID 35215472, 2022). "This locus is also known to harbour numerous mutations reportedly affecting insulin secretion through impairment of the KATP channel, which may eventually lead to hyperglycaemia and a wide spectrum of T2DM phenotypes." (PMID 36314849, 2022). "Thus, TD (a lipophilic form of vitamin B1) can improve hyperglycemia, which contributes to increased endogenous insulin secretion and decreased glucagon secretion." (PMID 35725834, 2022). "Cisapride administration significantly reduced blood glucose and increased serum insulin, suggesting that cisapride could reduce hyperglycemia in db/db mice." (PMID 36325440, 2022). "Furthermore, the effect of insulin administration must also be taken into account to interpret our results and not only the effect of hyperglycemia." (PMID 35578303, 2022). "Moreover, SalB reduces TG, FFA, and serum insulin levels, down-regulates hepatic gluconeogenic gene, and improves insulin intolerance, thus ameliorating dyslipidemia and hyperglycemia in db/db mice via the AMPK pathway." (PMID 36127704, 2022). "However, the β NF45−/− mice developed hyperglycaemia owing to the fall of insulin level in plasma compared with the control mice." (PMID 35614067, 2022). "Rebound hyperglycemia during the post-HD period may be related to choices of dialysate and dialysis membrane, which can influence plasma insulin concentrations during dialysis." (PMID 35528010, 2022). "Combining the HFD with a higher dose of STZ (120 mg kg−1) resulted in the development of frank hyperglycaemia and hypoinsulinaemia (but not loss of insulin) at the same time as the retention of an obese and hyperlipidaemic phenotype." (PMID 35128667, 2022). "Persistent fasting and postprandial hyperglycemia in diabetic complications increase flux through the HBP and associated protein O-GlcNAcylation, which results in increased endogenous glucosamine that impairs insulin action and triggers oxidative stress." (PMID 36466390, 2022).
Hyperglycemia (continued). "Adding insulin to PN is a convenient and physiologically favorable method to treat hyperglycemia." (PMID 36992742, 2022). "Moreover, fasting blood glucose and HbA1c were significantly higher in patients with DPN, which requires a variety of clinical strategies to reduce hyperglycemia, including insulin therapy." (PMID 36611296, 2022). "Ground-breaking work from Roger Unger and colleagues showed that the disruption of the glucagon-insulin bi-hormonal relationship may contribute to hyperglycemia in the diabetic condition." (PMID 35547006, 2022). "In ICUs, insulin is primarily preferred in the treatment of steroid-induced hyperglycemia." (PMID 35582516, 2022). "In 1920 Jorgen Petersen formulated the hypothesis that maternal hyperglycaemia leads to increased glucose levels in the fetus which in turn stimulates fetal pancreatic insulin secretion leading to fetal hyperinsulinaemia." (PMID 35258482, 2022). "Because INL and ONL contain various neuronal cell bodies of retinal cells, thinning of the INL by both liraglutide and insulin–hydralazine treatment and that of ONL by insulin–hydralazine treatment evokes a decrease in intracellular edema via the attenuation of hyperglycemia and hypertension." (PMID 35524186, 2022). "When treated with DKA, during insulin infusion, rapid correction of prolonged hyperglycaemia may increased the inability of the red blood cells to produce NADPH." (PMID 35313968, 2022). "Thus, precise control of the amount and rate of INS released into the blood in order to maintain the BGL within the narrow concentration window required to avoid hyperglycemia and hypoglycemia is challenging." (PMID 36246353, 2022). "Therefore, insulin resistant individuals have a decreased capacity to store plasma glucose as muscle and liver glycogen and suppress hepatic gluconeogenesis in response to insulin, commonly resulting in simultaneous hyperinsulinemia and hyperglycemia." (PMID 35244142, 2022). "Notably, adjunctive exenatide therapy has been shown to decline postprandial hyperglycemia in adolescents with T1DM even in the presence of reduced insulin dose; thus, exenatide bears significant therapeutic potential for adjunctive treatment of T1DM." (PMID 36514009, 2022). "The reason for hyperglycaemia is believed to be a high ability to mobilize glucose from hepatic glycogen stores and may also reflect insulin resistance." (PMID 36114619, 2022). "The disease causes hyperglycemia secondary to insulin deficiency, which becomes lethal over time without insulin replacement therapy." (PMID 35956384, 2022). "Two episodes of hyperglycemia occurred thereafter for which insulin treatment was given." (PMID 36542240, 2022). "Hyperglycemia stimulates tumor growth by inducing the increase of insulin and IGF-1 levels." (PMID 35907868, 2022). "It is also possible that the SNPs increase the ratio between soluble and membrane-bound IR, which may lead to hyperglycaemia because sIR competes with membrane-bound IR for insulin." (PMID 35742925, 2022). "However, stress hormone response results in persistent insulin resistance and hyperglycemia and this directly favors SARS-CoV-2 replication in human monocytes." (PMID 36422255, 2022). "Clinical management innovations such as the introduction of a nurse-led implementation of an intravenous insulin protocol showed a significantly reduced length of stay (4.9 days) in addition to improved target glucose range and reduced hyperglycaemia and hypoglycaemia events." (PMID 36992734, 2022). "The binding of insulin and its receptors on the surface of osteoblasts stimulated the secretion of OCN, which in turn promoted the proliferation of β-cells in the pancreas and insulin sensitivity, however, hyperglycemia and high levels of ROS regulated the production of OCN negatively." (PMID 36297386, 2022).
Hyperglycemia (continued). "In a study using streptozotocin (STZ)-induced diabetic rats, COS was able to treat hyperglycemia at a dose of 1000 mg/kg by lowering fasting serum glucose and insulin levels, thus improving O-glycosyltransferase (OGT), enhancing the index of insulin sensitivity, and reducing insulin resistance." (PMID 36080631, 2022). "Therefore, consistent with our previous finding that insulin infusion administered to patients to correct hyperglycaemia also reverses NO resistance, it is likely that increased insulin effect occurs in some Px-treated patients with similar outcomes." (PMID 36289640, 2022). "Hyperglycemia inactivates the glucose transporters (GLUT) which are normally triggered by insulin." (PMID 35326383, 2022). "Similarly, chronic hyperglycemia is the condition of persistent and unusually high postprandial (after a meal) blood glucose levels, primarily due to the flawed insulin production." (PMID 35204122, 2022). "These transporters exhibit regional heterogeneity in the brain tissue and their expression is regulated at transcriptional, post-transcriptional and post-translational levels by external stimuli, including hypoxia, insulin, hyperglycemia and hypoglycemia, and increased brain glucose demand." (PMID 36619556, 2022). "This includes effective control of blood glucose or insulin levels, enhancement of insulin tissue sensitivity, improvement of blood lipid profiles, and protecting against organ damage under sustained conditions of hyperglycemia." (PMID 35899107, 2022). "He presented with growth retardation, peculiar facial features, acanthosis nigricans, hypertrichosis, extremely high insulin levels, fasting hypoglycemia, and postprandial hyperglycemia, Whole-exome gene testing suggested compound heterozygous mutations in INSR (c.2246delG and c.2646 + 5G > A)." (PMID 36626508, 2022). "Notably, pro-inflammatory mediators can induce maternal hyperglycaemia during GDM by reducing whole-body insulin sensitivity and glucose utilisation, by disrupting insulin signalling pathways in skeletal muscle and white adipose tissue." (PMID 36014792, 2022). "It had extremely low levels of insulin, severe hyperglycemia, and low body weight." (PMID 36699319, 2022). "Indeed, it has been demonstrated that chronic replenishment of adipsin in diabetic db/db mice preserves β-cell mass by blocking β-cell death and dedifferentiation, thus increasing insulin levels and ameliorating hyperglycemia." (PMID 35628332, 2022). "Hyperglycemia produces reactive oxygen species (ROS) that are responsible for the development of oxidative stress and contributes to the impairment of insulin action and insulin secretion." (PMID 35502173, 2022). "We postulate that the relatively insufficient insulin secretion in this subgroup may be partly attributable to glucotoxicity and lipotoxicity, given the uncontrolled hyperglycaemia, overt dyslipidaemia and abnormal lipidomics profile." (PMID 35763031, 2022). "Therefore, α-syn can possibly aggravate hyperglycemia both at the insulin secretion sites and at the receptor sites." (PMID 35255986, 2022). "In summary, current evidence suggests that UA possesses potential therapeutic activity in improving insulin sensitivity, hyperglycemia, and inflammation, in addition to its protective role such as receptor modulator, enzyme inhibitor, or in neurotransmitter uptake." (PMID 35213966, 2022). "Therefore, treating hyperglycemia with insulin is the key to reducing intraoperative adverse events." (PMID 36088294, 2022). "Perhaps it is these depleted stores that alter the insulin response to ingested or infused glucose; instead maintaining low blood insulin concentrations during exercise even though the glucose infusions in these experiments produced a profound hyperglycemia." (PMID 35215511, 2022). "α-Spinasterol isolated from A. pseudoglehnii may improve hyperglycemia by improving glucose uptake into skeletal muscle cells and enhancing insulin secretion in pancreatic β-cells." (PMID 35270128, 2022).